DPP4 (dipeptidyl peptidase 4)
Diseases named in the same sentence as DPP4 in open-access papers (continued):
Sharing a sentence is not in itself a finding about the gene and the disease.
tumor (continued). "In addition, CD26/DPP4 cleaves ligands CXCL10 and CXCL12, which play a role in lymphocyte migration and tumor immune surveillance, thus increasing susceptibility to metastasis." (PMID 34055551, 2021). "Moreover, the correlation between DPP4 expression and the marker genes of immune cells implicates the role of DPP4 in regulating tumor immunology in LUSC." (PMID 33614513, 2021). "DPP4 expression was positively correlated with infiltrating levels of various immune cells and showed strong correlations with diverse immune marker sets in pan-cancer patients analyzed by Tumor Immune Estimation Resource (TIMER)." (PMID 33614513, 2021). "DPP4 has been shown to be a tumor suppressor in other cancers, such as melanoma and ovarian cancer." (PMID 34955820, 2021). "DPP4 knockout enhanced killing of tumor cells by neutrophils compared to the scrambled control." (PMID 34378358, 2021). "In addition, there was statistically significant correlation between variation in serum titer of DPP4 enzymatic activity and tumor volume or PFS, similar to the case with serum sCD26 titer." (PMID 33757558, 2021). "Overall, reducing DPP4 activity with sitagliptin reduced metastatic tumour burden in vivo." (PMID 33513866, 2021). "The combination of DPP4 with plasminogen 2-epsilon could promote the secretion of matrix metalloproteinases (MMPs), which are involved in tumor invasion." (PMID 34955820, 2021). "Recent data suggest that DPP4 may act as a tumor suppressor gene to the AR pathway, and that DPP4 inhibition can result in emergence of resistance to ADT." (PMID 34055551, 2021). "In the current study, we sought to determine whether DPP4 inhibition using sitagliptin enhances lymphocyte tumour infiltration in a syngeneic mouse model of EOC to abrogate tumour-mediated immune suppression and promote antitumour immunity." (PMID 33513866, 2021). "The differences in DPP4 effects might be attributed to the tumor microenvironment and the complex functions of the molecule." (PMID 34955820, 2021). "Nevertheless, the effects of DPP-4 inhibitors on tumor metastasis remain unknown and further investigation is important." (PMID 34063285, 2021). "Recent work demonstrated that DPP4 inhibition can delay tumour progression in other malignancies." (PMID 33513866, 2021). "CD26/DPP4 has been implicated in the modulation of T-cell activation and proliferation and CD26/DPP4-positive T cells are characterized by remarkable anti-tumor properties rendering them interesting candidates for T cell-based immunotherapies." (PMID 34885056, 2021). "This is the first finding that the serum sCD26/DPP4 titer variation in the early phase of treatment with the humanized anti-CD26 antibody YS110 may be a predictive biomarker for anti-tumor activity for patients with CD26+ cancers including MM." (PMID 33757558, 2021). "As the tumor grade increased, DPP4, HMOX1, and TFRC expression levels also increased." (PMID 35154262, 2021). "The decreased level of DPP4 in AG was further validated using an independently-collected cohort, as well as by comparison with a TCGA mRNA dataset and the immunohistochemical stains using our tumor microarray (TMA)." (PMID 34556748, 2021). "In addition to the elevated level of endogenous GLP-1, DPP-4 inhibitor administration increases numerous substrates that also influence the tumor microenvironment and the immune system, which are essential for tumor onset." (PMID 34063285, 2021). "Moreover, upon immune checkpoint blockade in mice, CD26/DPP4 is upregulated only in TIL from those animals that mounted an efficient anti-tumor response." (PMID 34885056, 2021). "The safety profile of DPP-4 inhibitors for a cardiovascular event in T2DM patients has been widely analyzed; however, a clear association between DPP-4 inhibitors and tumor biology is not yet established." (PMID 34063285, 2021). "The overexpression of DPP-4 in several cancers induces an anti-tumor effect." (PMID 34063285, 2021).
tumor (continued). "Real world evidence and reports of observational evidence of impact of DPP4 inhibitors in tumor patients in the setting of COVID-19 infection are required to make definite conclusions with regards to the whether they are beneficial." (PMID 33614513, 2021). "Furthermore, DPP4 levels increased significantly in circulation and adipose tissue in obese patients and some specific tumor patients." (PMID 33614513, 2021). "DPP4 can truncate CXCL10 to modify CXCL10–CXCR3 mediated influx of killer T cells in tumours." (PMID 34771657, 2021). "Silencing of DPP4 significantly suppressed tumor growth in the liver compared to the control." (PMID 34378358, 2021). "Furthermore, CXCL10 has shown great anti-tumor potential; thus, we further showed that DPP4 was correlated with CXCL10, a novel anti-tumor chemokine, through physical interaction and co-expression by GENEMANIA analysis." (PMID 33614513, 2021). "Thus, DPP4 function is altered according to specific location, histologic type of tumor, tumor microenvironment, and cofactors." (PMID 34955820, 2021). "Our data suggest that targeting the DPP4 enzyme family may be a novel and effective approach to promote anti-tumour immunity in HCC via caspase-1 activation." (PMID 34771657, 2021). "In view of these findings, our data showing that serum DPP4 activity was decreased following YS110 treatment would suggest enhancement of tumor immunity via DPP4 inhibition may constitute yet another mechanism of action of YS110." (PMID 33757558, 2021). "In the present study, scatter plot analysis of the relationship between serum sCD26/DPP4 titer variation and tumor volume variation by RECIST response criteria suggested that a predictable time period during the course of YS110 treatment can be used to distinguish between SD and PD cases." (PMID 33757558, 2021). "The currently known mechanism of sitagliptin‐mediated tumor suppression mainly involves the function of sitagliptin as a DPP4 inhibitor, which can inhibit epithelial‐mesenchymal transition and tumor metastasis by inhibiting DPP4 expression, thereby improving tumor immunity and immunotherapy." (PMID 32227453, 2020). "The current study explored the contributions of the lncRNA MCM3AP-AS1 in tumor-associated inflammation and angiogenesis in ccRCC with a specific focus on its transcriptional regulation and its interactions with transcription factor E2F1 and DPP4." (PMID 32714856, 2020). "In addition, a patient-derived xenograft (PDX) model was used to assess the correlation between DPP4 expression and tumor growth in vivo." (PMID 32294701, 2020). "More importantly, we observed that HCC tissues with low DPP4 expression had more rapid tumor growth than HCC tissues with high DPP4 expression using the PDX model, and this result indicated that DPP4 may act as a tumor suppressor gene for HCC." (PMID 32294701, 2020). "Importantly, whilst the mechanism of hypoxia-induced DPP4 regulation also occurs in non-malignant cells, our data shows that the enzymes regulating DPP4 function differ in malignancy and suggest complex regulation of DPP4 in tumour versus non-tumour tissues." (PMID 33143089, 2020). "Furthermore, we also documented elevated levels of DPP4 in ccRCC, wherein MCM3AP-AS1 promoted tumor inflammation and angiogenesis of ccRCC by upregulating DPP4." (PMID 32714856, 2020). "Also, the correlation analysis of MCM3AP-AS1 and DPP4 expression was performed in 78 ccRCC tumor tissues, and MCM3AP-AS1 and DPP4 were found to be positively-correlated in ccRCC tumor tissues (r = 0.519, p = 0.001)." (PMID 32714856, 2020). "TNM stage, tumor number, and vascular invasion correlated with DPP4 expression." (PMID 32294701, 2020). "Thus, inhibition of DPP4 enzymatic activity by DPP4 inhibitors would limit degradation of chemokines, enhance tumor infiltration by T cells, and tumor cell killing." (PMID 31124302, 2019).
tumor (continued). "We believe that DPP4/CD26 exerts its effects on tumor cells by interacting with immune cells through chemokines, but exact mechanisms are still unknown." (PMID 31124302, 2019). "A recent study reported that dipeptidyl peptidase 4 inhibitor could recruit eosinophils into the tumor tissue and inhibit its growth, which could be a potential explanation for the role of eosinophils in anti-tumor reactions." (PMID 31805879, 2019). "In addition, an experimental mouse model revealed that inhibition of DPP4 lead to reduced tumor burden by favoring the intra-tumor migration of effector Th1 cells." (PMID 30026741, 2018). "In the setting of cancer, it has recently been proposed that DPP4 inhibitors could enhance trafficking of anti‐tumour immune cells into the lesions." (PMID 29987877, 2018). "This implicates that DPP4 can promote tumor cell migration and invasion." (PMID 27936466, 2017). "Due to its multiple functions, CD26/Dipeptidyl peptidase 4 has been shown to be related to the tumor-development process, but it remains unclear if it is a tumor suppressor or a marker of malignancy." (PMID 27528223, 2016). "It has been shown that DPP4 may have a critical function in tumor progression in several human malignancies." (PMID 20540791, 2010). "Immunodeficient NSG mice were used to examine whether DPP4 influences tumor growth in vivo." (PMID 41283988, 2025). "Furthermore, targeted inhibition of DPP4 delayed tumor recurrence in combination with EGFR‐TKIs." (PMID 40479551, 2025). "Regarding Dipeptidyl Peptidase-4 (DPP-4) inhibitors, by virtue of its possible action on many proteins, a wealth of mechanisms have been discussed with potential influence on cancer biology, both as a suppressor as well as an inducer of tumor transformation and proliferation." (PMID 40277890, 2025). "Therefore, we speculated that paclitaxel mainly inhibited DPP4 expression in the tumor cells to upregulate the sICOSL levels." (PMID 40708008, 2025). "Moreover, DPP4 levels were markedly increased in the subcutaneous tumor tissues post‐treatment, which simulated the minimal residual disease (MRD), as well as in the orthotopic tumors receiving osimertinib and residual lesions from patients after EGFR‐TKIs treatment." (PMID 40479551, 2025). "In addition, DPP-4 enzyme was reported to be involved in tumor metastasis and invasion." (PMID 40786041, 2025). "Therefore, we confirm that miR-570-3p exerts a tumor-suppressive effect in PTC by inhibiting DPP4." (PMID 38890707, 2024). "However, the DPP4 activity can cut proangiogenic chemokines, and this unresolved issue may be important in the tumor development." (PMID 39001488, 2024). "Additionally, in The Cancer Genome Atlas (TCGA) database, we observed that lower DPP4 expression levels were correlated with higher Gleason scores, advanced cT and pathological stages, tumour metastasis, and shorter progression‐free survival rates in PCa patients." (PMID 37533175, 2023). "In summary, we demonstrated for the first time that the DPP4 inhibitor, anagliptin, plays an anti-tumor role as an ROS scavenger by inhibiting macrophage differentiation and M2 macrophage polarization, and it can potentiate the anti-tumor effect of PD-L1 blockade in NSCLC." (PMID 37115489, 2023). "Notably, DPP4 expressed higher in advanced tumor stages than in the early stage (p < 0.05)." (PMID 36467461, 2022). "THCA with high expression of DPP4 may be an immune-active tumor and is suitable for immunotherapy." (PMID 36467461, 2022). "Moreover, it is unknown whether DPP-4 inhibitors influence existing tumor growth, metastasis, and chemotherapy resistance because these trials excluded cancer-bearing diabetic patients." (PMID 34063285, 2021). "Interestingly, we found that the expression levels of most marker sets of tumor-associated macrophages, M2 macrophages, but not M1 macrophages, were strongly correlated with DPP4 expression in LUSC." (PMID 33614513, 2021).
tumor (continued). "Unexpectedly, DPP4 localization was also altered; in untreated tumours, DPP4 staining was largely associated with the periphery of tumour mass, whilst in sitagliptin-treated mice, peripheral localization was absent and DPP4 staining was localised inside the tumour mass." (PMID 33513866, 2021). "However, the expression of DPP4 and its functions in tumors differ according to tumor type." (PMID 34955820, 2021). "These include some of the tumor associated proteins with differential levels in both stage IIIA and IVB such as alkaline phosphatase, tissue-nonspecific isozyme isoform 1 preproprotein (ALPL), dipeptidyl peptidase 4 isoform X1 (DPP4), protein TFG isoform X2 (TFG)." (PMID 34876625, 2021). "On the one hand, DPP4 may act as a tumor suppressor in malignant diseases." (PMID 34955820, 2021). "Therefore, we explored whether DPP4 expression correlated with an immune storm in tumor patients such as LUSC." (PMID 33614513, 2021). "In addition to the mechanisms of action responsible for the anti-tumor activity of YS110 recent works demonstrated the functional role of DPP4-mediated post-translational modification of chemokines in regulating tumor immunity through its interaction with its substrates." (PMID 33757558, 2021). "Notably, HCC tissues with low expression of DPP4 had poor OS (P=0.016) compared with HCC tissues with high expression of DPP4, and results from PDX model showed that tumor growth was significantly faster in HCC patients that lowly expressed DPP4 compared to those with highly expressed DPP4." (PMID 32294701, 2020). "Moreover, recent in vivo work performed in mice has demonstrated that this truncation alters lymphocyte migration and limits infiltration of the tumor parenchyma, a phenomenon that could be reversed using the DPP4 inhibitor sitagliptin." (PMID 27137491, 2016). "Consistent with a key role for CD8+ T-cell immunity, the antitumor effect of anti–PD-1 therapy in the DPP4-reconstituted group was abolished by CD8+ T-cell depletion, resulting in renewed tumor growth." (PMID 41283988, 2025). "The effects of DPP-4 inhibitors (DPP-4i) on postoperative outcomes and tumor biology in diabetic patients with colorectal cancer (CRC) were investigated in a retrospective study involving 260 patients with T2D who underwent curative resection for CRC." (PMID 40282969, 2025). "We analyzed tumor infiltration to determine if DPP4 promotes or suppresses tumor growth and affects the TME through immune cell activity, suggesting DPP4 as a potential therapeutic target in PCa." (PMID 40766751, 2025). "Among them, the expression of TIPRAP, WSCD1, TCP11L2, DPP4, CAB39 and PDPK1 were down-regulated, while PARP1, DEPDC1B, CKAP2, ORMDL2, MRPL44, POLD4 and TMEM187 were increased in tumor group." (PMID 39949782, 2025). "CD26 (DPP-4) is a multifunctional transmembrane glycoprotein with known roles in immune regulation, enzymatic cleavage of peptides, and tumor progression." (PMID 40806753, 2025). "Upon light exposure, 1O2 cleaved the thioketal linker to release sitagliptin, which inhibited DPP4 activity, suppressed DPP4-mediated degradation of the eosinophil-recruiting chemokine CCL11, and upregulated tumor-infiltrating eosinophils." (PMID 40363042, 2025). "In summary, DPP4 was a significantly up‐regulated marker in both DTP and c‐DTP cells, with elevated levels also observed in patient tumor tissues treated with EGFR‐TKIs." (PMID 40479551, 2025). "The role of dipeptidyl peptidase-4 (DPP-4) in cancer remains complex and controversial, as studies have reported both tumor-promoting and tumor-suppressing effects." (PMID 40282969, 2025). "EC-C4 highly expressing DPP4 interacted with TAMs expressing chemokines CXCL10 and CXCL11, especially CXCL11+ TAMs, thereby inhibiting their anti-tumor immune response." (PMID 39232806, 2024). "Consequently, tumor immunity may change significantly owing to DPP4 inhibition." (PMID 38672409, 2024).
tumor (continued). "DPP4 is a multifunctional cell surface protein reported to play a pivotal role in various cancer types, including CRC, through its interaction with the tumor microenvironment and is widely expressed in the T-lymphocytes." (PMID 38203779, 2024). "DPP4 modulates chemokines by cleaving CCL11, reducing eosinophil infiltration and T-cell-independent anti-tumour responses." (PMID 39451776, 2024). "In terms of upregulated DEGs, seven genes (ABI3BP, CTSG, DPP4, CCL18, OSR2, GRIA3, MMP2) demonstrated reduced expression in tumor compared to normal tissue." (PMID 39062832, 2024). "mMDSCs in the GBM TME of humans and mice expressed higher levels of adhesion molecules, such as integrin β1 and dipeptidyl peptidase 4 (DPP4), leading to enhanced cell adhesion and further promoting tumour migration and invasion." (PMID 38130720, 2023). "It has also been reported that inhibition of the enzymatic activity of DPP4 promotes infiltration of CXCR3-expressing T cells into tumor tissues and enhances their anti-tumor effects." (PMID 37218983, 2023). "The molecule CD26 is a 110 kDa type II glycoprotein anchored to the membrane, with dipeptidyl peptidase 4 (DPP4) enzymatic activity, expressed by various cells involved in immunological processes and tumor regulation." (PMID 37170241, 2023). "For instance, exosomal dipeptidyl peptidase IV (DPP4) has been identified as an inducer of angiogenesis via activation of SMAD signaling pathway and its inhibition has been shown to suppresses tumor growth in vivo." (PMID 35292091, 2022). "The search terms “ectoprotease”, “cell surface protease”, “DPP4/CD26”, “FAP/Seprase”, “APN/CD13”, “ADAM17/TACE”, “MMP/gelatinase”, “drug”, “inhibitor”, “clinical trial”, “metabolism”, “tumour”, “microenvironment” were employed for this purpose." (PMID 35158891, 2022). "We further analyzed the role of DPP4, CTNNB1, and MET expressions in promoting THCA progression and tumor metastasis." (PMID 35205190, 2022). "Several preclinical studies have addressed the potential link between DPP-4/CD26 and tumor progression." (PMID 34063285, 2021). "Inhibition of DPP4, DPP8, DPP9 and FAP by Val-boroPro has been shown to mediate regression in multiple tumour models, likely, at least in part, via the modulation of immune responses." (PMID 34771657, 2021). "DPP4 inhibition blocks the cleavage of CXCL10 by DPP4, thereby increasing the chemotaxis of immune cells towards tumour tissue via the cognate receptor of CXCL10, CXCR3." (PMID 34771657, 2021). "We then performed a trans‐well migration assay with active CXCL6 or DPP4‐truncated CXCL6 in the lower chamber and neutrophils isolated from the tumor‐bearing mouse in the top chamber." (PMID 34378358, 2021). "In line with in vitro findings, sitagliptin treatment (alone or combined with MTX) effectively reduced DPP4 enzymatic activity, inhibited cholesterol biosynthesis and DHCR24 expression, and suppressed tumor growth in JAR/MTX xenograft model." (PMID 34926239, 2021). "The inhibition of DPP4 preserves the CXCL10 chemokine and enhances the tumor immunity and the migration of T-cells to the tumor microenvironment." (PMID 35087404, 2021). "Compounds that inhibit the DPP4 enzyme family, such as talabostat and ARI-4175, can mediate tumour regression by immune-mediated mechanisms that are believed to include NLRP1 activation." (PMID 34771657, 2021). "Administration of the DPP4 inhibitor resulted in higher concentrations of CCL11 and increased migration of eosinophils into tumor parenchyma, enhancing the eosinophil-mediated anti-tumor responses." (PMID 33614513, 2021).